ARL13A (ARF like GTPase 13A)
Synonyms: ARL13; dJ341D10.2
Tractability: Antibody: the Human Protein Atlas places it where antibodies can reach.
Gene: Protein-coding gene on chromosome X (100,969,708 to 100,990,831, forward strand). Ensembl gene ENSG00000174225.
Subcellular location (Human Protein Atlas): Actin filaments; Connecting piece; Mid piece; Plasma membrane; Acrosome; Cytosol; Principal piece
Gene Ontology:
Molecular function: GTP binding; GTPase activity
Biological process: non-motile cilium assembly; receptor localization to non-motile cilium
Cellular component: ciliary membrane; motile cilium; non-motile cilium; 9+0 non-motile cilium
Homologues: Orthologues: chimpanzee ARL13A (99% identical), macaque ARL13A (95% identical), pig ARL13A (72% identical), rat Arl13a (67% identical), mouse Arl13a (63% identical), zebrafish arl13a (35% identical). Paralogues in human: ARL13B (35% identical), ARL2 (21% identical), ARL4A (20% identical), ARL11 (20% identical), TRIM23 (20% identical), ARL6 (19% identical), ARL4C (18% identical), ARF4 (18% identical), ARF6 (18% identical), ARL3 (18% identical), ARL4D (18% identical), SAR1B (18% identical), and 18 more.
Diseases named in the same sentence as ARL13A in open-access papers:
ARL13A is named in the same sentence as 2 diseases in open-access papers, as found by Europe PMC text mining. Sharing a sentence is not in itself a finding about the gene and the disease.
ARL13A shares sentences with these, for which no sentence is quoted: ciliopathy (4 papers); Joubert syndrome (2).